DHX9 (DExH-box helicase 9)
Diseases named in the same sentence as DHX9 in open-access papers (continued):
Sharing a sentence is not in itself a finding about the gene and the disease.
thyroid cancer (2 papers, 2021 to 2023). "Loss of function of DHX9 enhanced the proliferation, colony formation and migration of thyroid cancer cells." (PMID 34512155, 2021). "We first verified that DHX9 is highly expressed in most tumors but significantly decreased in kidney and thyroid cancers, and it is prominently correlated with the prognosis of patients with different tumors." (PMID 37214432, 2023). "In summary, MARCH6 significantly promotes thyroid cancer growth and migration by interacting with DHX9 and activating the AKT/mTOR pathway." (PMID 34512155, 2021). "The inhibitory effect of MARCH6 knockdown on thyroid cancer cell growth and migration was also reversed by DHX9 silencing." (PMID 34512155, 2021). "As expected, when MARCH6 knockdown suppressed proliferation, colony formation and migration, further silencing DHX9 reversed these phenotypes in thyroid cancer cells." (PMID 34512155, 2021). "Overall, MARCH6 functions as a potential oncogene in thyroid cancer by destabilizing DHX9 and activating AKT/mTOR signaling." (PMID 34512155, 2021). "Since MARCH6 silencing upregulated DHX9 in thyroid cancer cells, we interfered with DHX9 expression in cells with downregulated MARCH6." (PMID 34512155, 2021). "MARCH6 would interact with DHX9 and destabilize DHX9 in thyroid cancer cells." (PMID 34512155, 2021). "To determine the role of DHX9 in thyroid cancer, we used lentivirus to knock down DHX9." (PMID 34512155, 2021). "As our results showed, silencing DHX9 inhibited cell proliferation, migration and cell cycle progression and induced cell apoptosis in thyroid cancer cells, indicating that DHX9 acted as a tumor suppressor in thyroid cancer." (PMID 34512155, 2021). "Knockdown of DHX9 enhanced the proliferative and migratory abilities of thyroid cancer cells." (PMID 34512155, 2021). "Furthermore, we determined that MARCH6 could interact with DHX9 to regulate thyroid cancer cell growth and migration." (PMID 34512155, 2021). "Therefore, DHX9 is the substrate of MARCH6 in thyroid cancer." (PMID 34512155, 2021). "Therefore, DHX9 is likely a tumor suppressor in thyroid cancer." (PMID 34512155, 2021). "However, whether DHX9 plays important roles in thyroid cancer development is still unclear." (PMID 34512155, 2021). "However, DHX9 expression in tumor tissue was significantly lower than that in the normal control group in KICH (kidney chromophobe), KIRC (kidney renal clear cell carcinoma), KIRP (kidney renal papillary cell carcinoma), THCA (thyroid carcinoma)." (PMID 37214432, 2023).
acute myeloid leukemia (1 paper, 2023). Acute myeloid leukemia (AML) is a group of neoplasms arising from precursor cells committed to the myeloid cell-line differentiation. "We found that overexpression of DHX9 is frequent in MDS and associated with poor survival and high risk of acute myeloid leukemia (AML) transformation." (PMID 37305700, 2023).
Anxiety (1 paper, 2024). Intense feelings of nervousness, tension, or panic often arise in response to interpersonal stresses. "A decrease of DHX9 was observed in the hippocampus after peripheral nerve injury; overexpression of DHX9 in the hippocampus significantly alleviated the nociceptive responses and improved anxiety behaviors." (PMID 38327775, 2024). "Overexpression of DHX9 in mice with neuropathic pain notably attenuated their pain behaviors and comorbidity anxiety emotion." (PMID 38327775, 2024). "Moreover, we further assessed whether the upregulation of hippocampus DHX9 could alleviate the anxiety symptoms." (PMID 38327775, 2024).
avian influenza (1 paper, 2016). Infection of domestic and wild fowl and other birds with influenza A virus. "Avian influenza is particularly pathogenic in chickens because they are also deficient in another viral sensor, RIG-1 (DDX58), which is present in ducks and can partially compensate for the loss of DHX9." (PMID 27034008, 2016).
bladder cancer (1 paper, 2023). "Previous studies indicated that DHX9 might affect the metastasis of bladder cancer by promoting epithelial-mesenchymal transition (EMT)." (PMID 37214432, 2023).
bone marrow failure (1 paper, 2026). "Dhx9 deletion caused bone marrow failure and impaired hematopoietic reconstitution in murine primary and secondary transplantation recipients due to loss of HSCs and defective self-renewal capacity." (PMID 41650960, 2026).
colitis (1 paper, 2024). Inflammation of the colon. "Consistently, epithelial DHX9 deficiency also exacerbated disease severity in the TNBS-induced colitis model." (PMID 38594251, 2024). "Our rescue experiments demonstrated that blocking the cGAS-STING pathway partially rescues the colitis phenotype in Dhx9-deficient mice, supporting the idea that cGAS-STING activation contributes to colitis pathogenesis." (PMID 38594251, 2024). "It is noteworthy that even in a Sting knockout background, the additional deletion of DHX9 still led to a markedly more severe DSS colitis, as evidenced by the comparison between Dhx9ΔIECSting−/− mice and Sting−/− mice." (PMID 38594251, 2024). "Here, we observe reduced DHX9 protein levels in IBD patients, and mice with conditional DHX9 depletion in the intestinal epithelium (Dhx9ΔIEC) exhibit an increased susceptibility to experimental colitis." (PMID 38594251, 2024). "Additionally, our co-housing experiments suggested that the compromised regulation of commensal microbiota, attributable to DHX9 deficiency, plays a contributory role in the development of the DSS-induced colitis." (PMID 38594251, 2024). "To understand the role of DHX9 in adult ISC maintenance, we challenged Dhx9iΔISC mice and their Dhx9fl//fl littermates with 2.5% DSS to induce colitis." (PMID 38594251, 2024). "Collectively, these findings indicate that Paneth cell-specific DHX9 deletion has no significant impact on IEC lineage commitment or DSS-induced colitis." (PMID 38594251, 2024).
coronary artery disease (1 paper, 2023). "We find that DHX9 expression is significantly increased in oxLDL or interferon-γ-treated macrophages and peripheral blood mononuclear cells (PBMCs) from patients with coronary artery disease (CAD)." (PMID 37326773, 2023). "Our study firstly finds that DHX9 expression is significantly increased in oxLDL or interferon-γ-treated macrophages and peripheral blood mononuclear cells (PBMCs) from patients with coronary artery disease (CAD)." (PMID 37326773, 2023).
enteritis (1 paper, 2024). Inflammation of the small intestine. "However, direct knockout of DHX9 in Paneth cells did not affect the susceptibility of mice to enteritis." (PMID 38594251, 2024).
epilepsy (1 paper, 2020). A brain disorder characterized by episodes of abnormally increased neuronal discharge resulting in transient episodes of sensory or motor neurological dysfunction, or psychic dysfunction. "It is orthologous to the human DExH-box helicase 9 (DHX9) gene that is not related to epilepsy." (PMID 32899411, 2020).
heart failure (1 paper, 2023). Inability of the heart to pump blood at an adequate rate to meet tissue metabolic requirements. "Dhx9, Snrpd3, Erh, and Snrpd2l might be novel potential therapeutic targets for heart failure." (PMID 37405054, 2023).
Immunodeficiency (1 paper, 2021). Failure of the immune system to protect the body adequately from infection, due to the absence or insufficiency of some component process or substance. "Three of the factors were expressed at higher levels in ambiguous than in unambiguous cases—AHSG, TFRC, DHX9—and are involved in inflammation, innate immunity, and immunodeficiency, which are components of past infections." (PMID 33582300, 2021).
Intellectual disability (1 paper, 2024). "We further investigated the pathogenic potential of a novel heterozygous de novo missense mutation in DHX9 in a patient presenting with short stature, intellectual disability, and myocardial compaction." (PMID 39177028, 2024).
intestinal cancer (1 paper, 2024). "Thus, DHX9 deletion-induced genomic instability promoted the development of intestinal cancer." (PMID 38594251, 2024).
intrahepatic cholangiocarcinoma (1 paper, 2022). A carcinoma that arises from the intrahepatic bile duct epithelium in any site of the intrahepatic biliary tree. "DEx-H Box Helicase 9 (DHX9) is an RBP which is verified to disrupt the circularization of circRNA cGGNBP2 by binding to its flanking inverted complementary sequences in intrahepatic cholangiocarcinoma (ICC)." (PMID 35842651, 2022).
lipid metabolic disorders (1 paper, 2026). "Nevertheless, it remains uncertain whether Dhx9 can directly regulate p21 or other senescence genes, thereby influencing hepatocyte senescence and lipid metabolic disorders." (PMID 41114463, 2026).
metastatic tumors (1 paper, 2020). "However, we observed a significantly higher expression of DHX9 in metastatic tumors versus primary tumors (p = 6.2 × 103)." (PMID 32023846, 2020).
myeloid malignancies (1 paper, 2017). "Most of the significantly mutated genes were previously well documented either in MDS or other myeloid malignancies, although some were newly identified or re-confirmed as recurrently mutated genes in our analysis, such as ROBO1/2, IHIT3, KIF20B, PTPRD, ANKRD11 and DHX9." (PMID 28220884, 2017).
nasopharyngeal carcinoma (1 paper, 2025). A carcinoma arising from the nasopharyngeal epithelium. "CircCLASP2 increases the translation of protein-L-isoaspartate (D-aspartate) O-methyltransferase (PCMT1) through binding to nuclear DNA Helicase 9 (DHX9), which results in nasopharyngeal carcinoma (NPC) progression." (PMID 40710359, 2025).
neuropathic pain (1 paper, 2024). Chronic pain caused by damage to nerve fibers. "Collectively, our findings indicate that the downregulation of DHX9 might be universal in pain, especially in CCI-induced neuropathic pain." (PMID 38327775, 2024).
peripheral nerve injury (1 paper, 2024). Injury to a peripheral nerve. "Our findings enrich the current literature on the functional link between DHX9 and synapses in the context of pain and provide evidence that DHX9 may be a novel therapeutic target for peripheral nerve injury-induced neuropathic pain." (PMID 38327775, 2024).
reovirus infection (1 paper, 2020). "In myeloid dendritic cells (mDCs), both stable and transient knockdown of DexH-Box Helicase 9 (DHX9), leads to the decreased ability of these cells to secrete type I IFN following reovirus infection." (PMID 32575691, 2020).
synovial sarcoma (1 paper, 2021). "The expression levels of several key PRGs including CASP3, IL1B and DHX9 were significantly higher in the human synovial sarcoma cells SW-982 and hSS-005R, compared with those in the human skin fibroblast cell line (HSF)." (PMID 34925457, 2021).
thymus (1 paper, 2022). "We next investigated whether the severe thymus atrophy in Dhx9 cKO mice influenced peripheral T cell homeostasis." (PMID 35720303, 2022).
Werner syndrome (1 paper, 2017). "For example, Werner Syndrome helicase interacts with both N- and C-terminal regions of DHX9 to inhibit DHX9 activity." (PMID 28221134, 2017).
cancer (76 papers, 2009 to 2025). A tumor composed of atypical neoplastic, often pleomorphic cells that invade other tissues. "Our finding that depletion of DHX9 increased transcription of SMN2Sup was somewhat surprising given the role of DHX9 as an enhancer of transcription of several genes associated with cancer." (PMID 38214229, 2024). "Our present study reveals a significant association between DHX9 expression levels and the infiltration of various immune cells in different cancers, including CD4+ T cells, CD8+ T cells, neutrophils, B cells, DCs and macrophages." (PMID 37214432, 2023). "Our study demonstrates that DHX9 as a probable prognostic biomarker for various cancer types and it was associated with immune infiltration." (PMID 37214432, 2023). "DHX9 interacts with cancer-associated genes such as CBP, BRCA1 and EGFR to regulate their transcription and translation." (PMID 37305700, 2023). "DHX9 levels and interactions with oncogenes have been implicated in other types of cancers, such as breast and ovarian cancer, osteosarcoma, and Wilms’ tumor." (PMID 33952639, 2021). "Overexpression of DHX9 is a characteristic of some cancer types, and closely associated with the proliferation and metastasis of tumor cells and the prognosis of patients." (PMID 34676915, 2021). "Many different circRNAs have been associated with EMT in cancer cells, and DHX9 plays fundamental roles in modulating circRNAs during EMT." (PMID 33437516, 2020). "For example, an earlier study revealed proviral effects of DHX9 following its interaction with MYXV-encoded protein M029 in several human cancer cell lines, an action which promoted viral replication." (PMID 33437516, 2020). "The role of DHX9 in R-loop-associated DNA damage pointed toward its potential involvement in human cancer because one of cancer hallmarks is widespread genomic instability." (PMID 29742442, 2018). "DHX9 has been implicated to be involved in tumorigenesis of various cancers." (PMID 37214432, 2023). "Additionally, helicases such as DDX5, DDX20/DP103, and DHX9/DDX9 have also been implicated in cancer aggressiveness." (PMID 34708244, 2022). "DHX9 is also implicated in regulation of DNA transcription, translation, RNA processing and transport and maintenance of genome stability and is implicated in the development of many cancer types." (PMID 34946966, 2021). "Much effort has been expended lately in characterizing the association between DHX9 dysregulation and cancer development; however, there is still conflict as to whether it regularly functions as an oncogene or tumor suppressor." (PMID 34676915, 2021). "Defects in WRN and BLM, which resemble DHX9 in their substrate specificities, lead to rare autosomal recessive disorders characterized by premature aging, growth retardation, increased genome instability, and increased cancer susceptibility." (PMID 27034008, 2016). "Notably, DHX9 has been implicated in the tumorigenesis of various cancers." (PMID 39668816, 2024). "In cancer research, CARINH has been found to interact with transcriptional co-activators DHX9, ILF3 to regulate the expression of IRF1, with its loss contributing to tumor progression." (PMID 41283334, 2025). "Our previous study was the first to demonstrate that under replication stress, TUG1 is rapidly upregulated via ATR-CHK1 signalling and interacts with DHX9, playing a crucial role in resolving R-loops formed at replication forks in cancers." (PMID 40654306, 2025). "Knockdown of DHX9 significantly reduces tumor growth, while long-term suppression in adult mice is tolerated well, making DHX9 an excellent target for cancer treatment." (PMID 39941810, 2025). "Using the TCGA dataset, we observed that DHX9 mRNA levels were frequently raised in the majority of cancer types compared with adjacent normal tissues." (PMID 40659605, 2025).
cancer (continued). "ATX968, a newly developed small-molecule inhibitor of DHX9, exhibits tumor growth inhibition in cancers with microsatellite instability and mismatch repair deficiency." (PMID 40659605, 2025). "The nine genes identified in our signature (Dhx9, Dusp12, Fhl1, Ifitm1, Ndufs1, Pja2, Slc1a3, Soga1, and Spon2) have each been investigated for their role in cancer." (PMID 38193115, 2024). "In cancer cells, DHX9 has been shown to suppress dsRNA sensing and activation of MDA5, PKR and RNase L, thereby blocking downstream innate immune responses." (PMID 39221819, 2024). "Remarkably, the deletion of DHX9 leads to a substantial reduction in cancer cell viability in vitro and fosters a significant boost in immunogenicity in mouse models of small-cell lung cancer, thereby greatly enhancing the responsiveness to immunotherapy." (PMID 39668816, 2024). "While ADAR1, XRN1 and DDX3X are essential only in some cancer cell lines, DHX9 is more commonly essential across all cancer cell lines." (PMID 39221819, 2024). "After validated the expression pattern of DHX9 in human cancer, we also explored its function in cancer cells." (PMID 37214432, 2023). "Among these antiviral RNA helicases, we also reported that RNA helicase A (RHA) or DHX9 exits the nucleus in response to MYXV infection to form unique antiviral granules in the cytoplasm of infected human cancer cells." (PMID 37377603, 2023). "Seven proteins were reproducibly identified in two biological replicates and DHX9 attracted our attention for its role in cancer progression." (PMID 37041291, 2023). "In TIMER database, the corresponding heatmap showed that DHX9 was also positively correlated with these genes in most cancer types." (PMID 37214432, 2023). "In this study, we extracted pan-cancer data from TCGA and GEO databases to explore the prognostic and immunological role of DHX9." (PMID 37214432, 2023). "This function of DHX9 is helicase-dependent, and dysfunction of or misregulated DHX9 reshapes the global editing profile and contributes to cancer development." (PMID 36834609, 2023). "As the most significant immune checkpoint gene related to DHX9, we also examined the expression pattern of TGFβR1 in human cancers." (PMID 37214432, 2023). "DHX9 mediates the downregulation of circDCUN1D4, which is more common in clinically metastatic lymph nodes, resulting in a poor prognosis of cancer patients." (PMID 37214432, 2023). "In summary, this pan-cancer investigation provides a comprehensive understanding of the prognostic and immunological role of DHX9 in human cancers, and experiments indicated that DHX9 was a potential target for cancer treatment." (PMID 37214432, 2023). "It promotes cancer cell migration and angiogenesis by binding to the pro-oncogenic DHX9; in addition, lncRNA CCDST functions as a scaffold to promote the formation of MDM2 and DHX9 complexes to accelerate the degradation of DHX9." (PMID 36982798, 2023). "DHX9 knockdown in restricted human cancer cells significantly enhanced MYXV gene expression, progeny virus production, cell-to-cell spread, and foci formation." (PMID 37377603, 2023). "The prognostic value is a key property of an oncogene, so we investigated the prognostic value of DHX9 in cancers." (PMID 37214432, 2023). "Collectively, our study comprehensively characterized the expression pattern and prognostic role of DHX9 in pan-cancer." (PMID 37214432, 2023). "Functionally, DHX9 is involved in the expression and nuclear export of retroviral RNAs and is dysregulated in various cancers." (PMID 36690646, 2023). "Based on the TIMER database, we analyzed the correlation of DHX9 expression with immune infiltration levels in diverse cancer types." (PMID 37214432, 2023). "Similar results showed that DHX9 protein level in GC tissues was significantly upregulated compared to adjacent cancer tissues." (PMID 38041141, 2023). "In a variety of clinical and translational studies, DHX9 was confirmed as a prognostic gene for cancers." (PMID 36578944, 2022).